WDR83OS (WD repeat domain 83 opposite strand)
Description:
Component of the multi-pass translocon (MPT) complex that mediates insertion of multi-pass membrane proteins into the lipid bilayer of membranes. The MPT complex takes over after the SEC61 complex: following membrane insertion of the first few transmembrane segments of proteins by the SEC61 complex, the MPT complex occludes the lateral gate of the SEC61 complex to promote insertion of subsequent transmembrane regions. Within the MPT complex, the PAT subcomplex sequesters any highly polar regions in the transmembrane domains away from the non-polar membrane environment until they can be buried in the interior of the fully assembled protein (By similarity). Within the PAT subcomplex, WDR83OS/Asterix binds to and redirects the substrate to a location behind the SEC61 complex (By similarity).
Synonyms: PAT-10; PAT10; C19orf56; PTD008; ASTERIX; NEDFHCA
Tractability: Antibody: UniProt predicts a signal peptide or a membrane-spanning region. PROTAC: ubiquitination databases record sites on it.
Gene: Protein-coding gene on chromosome 19 (12,668,073 to 12,669,430, reverse strand). Ensembl gene ENSG00000105583.
Subcellular location: Endoplasmic reticulum membrane
Subcellular location (Human Protein Atlas): Endoplasmic reticulum
Gene Ontology:
Molecular function: protein binding; protein folding chaperone
Biological process: multi-pass transmembrane protein insertion into ER membrane; protein insertion into ER membrane; protein folding
Cellular component: endoplasmic reticulum membrane; multi-pass translocon complex; protein folding chaperone complex
Genetic constraint (gnomAD): Loss-of-function variants: 15 observed, 14.34 expected, observed/expected ratio (o/e) 1.05, 90% interval 0.7 to 1.6. The upper end of that interval is the gene's LOEUF score, 1.6, which puts it in group 6 of 6, group 1 being the genes least tolerant of losing a copy. Missense variants: 145 observed, 149.79 expected, observed/expected ratio (o/e) 0.97, 90% interval 0.85 to 1.11. Synonymous variants: 68 observed, 55.95 expected, observed/expected ratio (o/e) 1.22, 90% interval 1 to 1.49.
Homologues: Orthologues: chimpanzee WDR83OS (100% identical), dog WDR83OS (100% identical), guinea pig WDR83OS (100% identical), mouse Wdr83os (100% identical), rat Wdr83os (100% identical), pig WDR83OS (88% identical), zebrafish wdr83os (88% identical), tropical clawed frog wdr83os (86% identical), Drosophila melanogaster CG10674 (67% identical), Caenorhabditis elegans K10B2.4 (63% identical).
Diseases named in the same sentence as WDR83OS in open-access papers:
WDR83OS is named in the same sentence as 2 diseases in open-access papers, as found by Europe PMC text mining. Sharing a sentence is not in itself a finding about the gene and the disease. The quoted sentences say what the papers report.
Intellectual disability (1 paper, 2021). "For the other subunit of the PAT complex, Asterix (WDR83OS), a recessive variant has been reported to cause an unspecified syndrome with intractable itching, facial dysmorphia, microcephalus, hypercholanemia, short stature, and intellectual disability." (PMID 35008565, 2021).
WDR83OS also shares sentences with these, for which no sentence is quoted: melanoma (1 paper).